RNU6-821P (RNA, U6 small nuclear 821, pseudogene)
Gene: Small nuclear RNA gene on chromosome 3 (198,071,311 to 198,071,417, reverse strand). Ensembl gene ENSG00000212297.
Homologues: Orthologues: macaque U6 (88% identical), chimpanzee U6 (86% identical), dog U6 (68% identical), rat LOC120101210 (61% identical), mouse Gm22279 (60% identical), mouse Gm54642 (58% identical). Paralogues in human: RNU6-316P (90% identical), RNU6-55P (90% identical), RNU6-954P (89% identical), RNU6-1193P (87% identical), RNU6-1269P (87% identical), RNU6-368P (87% identical), RNU6-538P (87% identical), RNU6-798P (87% identical), RNU6-1320P (86% identical), RNU6-599P (86% identical), U6 (86% identical), U6 (85% identical), and 1287 more.